NPY2R (neuropeptide Y receptor Y2)
Diseases named in the same sentence as NPY2R in open-access papers (continued):
Sharing a sentence is not in itself a finding about the gene and the disease.
Parkinson disease (1 paper, 2017). A progressive degenerative disorder of the central nervous system characterized by loss of dopamine producing neurons in the substantia nigra and the presence of Lewy bodies in the substantia nigra and locus coeruleus. "The NPY2R gene has been shown to serve in a neuroprotective role in animal models of Parkinson’s disease." (PMID 27188386, 2017).
prostate carcinoma (1 paper, 2025). A carcinoma that arises from epithelial cells of the prostate gland. "Last, immunohistochemical analysis of human patients with prostate cancer found that NPY, NPY1R, NPY2R, and NPY5R expression was all significantly increased at the invasive border relative to the bulk tumor mass." (PMID 40073121, 2025).
Stroke (1 paper, 2026). Sudden impairment of blood flow to a part of the brain due to occlusion or rupture of an artery to the brain. "We hypothesised that greater weight loss by co-activation of GLP-1R/NPY2R would have a greater effect on post-stroke recovery than semaglutide monotherapy." (PMID 41094027, 2026). "Finally, we show that the same pharmacological strategies that are efficacious in improving stroke recovery through pre-stroke weight loss (via GLP-1R/NPY2R) can additionally provide acute neuroprotective effects post-stroke, independently of weight loss induction." (PMID 41094027, 2026). "We conclude that GLP-1R and NPY2R activation alone or in combination exhibit additional neuroprotective effects when administered acutely after stroke." (PMID 41094027, 2026). "Importantly, both interventions improved functional recovery after stroke to a similar extent, without affecting infarct size, indicating that enhanced stroke recovery by GLP-1R and NPY2R activation occurs entirely via weight loss." (PMID 41094027, 2026). "Finally, GLP-1R and NPY2R activation can also improve stroke recovery through acute neuroprotection if they are given acutely after stroke, independently of their metabolic effects." (PMID 41094027, 2026). "The effects of semaglutide on stroke recovery could be further potentiated by NPY2R activation." (PMID 41094027, 2026).
urothelial carcinoma (1 paper, 2017). A malignant neoplasm derived from the transitional epithelium of the urinary tract (urinary bladder, ureter, urethra, or renal pelvis). "Significant associations between cumulative arsenic exposure and the methylation level of the NPY2R gene have been observed in smoking-unrelated urothelial carcinomas." (PMID 29100314, 2017).
vasculitis (1 paper, 2021). "Third, via MCODE program we have discovered the protein interaction network between CCL4 and NPY2R, future analysis should more concentrate on underlying up/down regulation between them which might be the mechanism leading to vasculitis moreover vascular deteriorations in BD." (PMID 34975900, 2021). "In vasculitis related to BD, NPY2R expression is potentially impaired and may be a marker of vascular complications." (PMID 34975900, 2021).
Vertigo (1 paper, 2024). An abnormal sensation of spinning while the body is actually stationary. "(i) Identify vertigo-/syncope-prone individuals in the human population and determine the sequence of their NPY2R to detect differences from the clinically normal cohorts." (PMID 39000068, 2024).
tumor (3 papers, 2017 to 2026). "Mechanistically, Npy2r-expressing vagal sensory nerves transmit signals from lung tumours to brainstem nuclei, driving elevated sympathetic efferent activity in the tumour microenvironment." (PMID 41639447, 2026). "Remarkably, we found that the mode of therapy, HPV status, smoking status, alcohol intake, tumor stage, and gene methylation status all indicated the likelihood of recurrence in patients with methylated NPY1R and NPY2R promoters." (PMID 29100314, 2017).
central nervous disease (1 paper, 2021). "There are several up-regulated genes within the hippocampus, such as BDNF, NPY2R, and Gria1, and downregulated genes such as Arc, which are well known in the neural plasticity and pathogenesis of central nervous disease and abnormal behavior." (PMID 34045967, 2021).
infection (1 paper, 2025). The state of being infected such as from the introduction of a foreign agent such as serum, vaccine, antigenic substance or organism. "After 96 h of infection, we observed the merge of red fluorescence signal and green fluorescence signal in nodose ganglia and NTS, indicating the potential projection of Npy2r vagal sensory neurons innervating lungs to vlPAG." (PMID 40874463, 2025).
NPY2R also shares sentences with these, for which no sentence is quoted: diabetic retinopathy (2 papers); metabolic syndrome (2); neurodevelopmental disorder (2); Abdominal obesity (1); acne vulgaris (1); African trypanosomiasis (1); Alzheimer disease (1); cancer (1); end-stage renal disease (1); Insulin resistance (1); malaria (1); malignant glioma (1); melanoma (1); metabolic disorders (1); Neurologic Disease (1); oral cavity cancer (1); osteoporosis (1); pancreatic cancer (1); paraganglioma (1); renal carcinoma (1); T-cell acute lymphoblastic leukemia (1); Tinnitus (1).